CXCL11 (C-X-C motif chemokine ligand 11)
Diseases named in the same sentence as CXCL11 in open-access papers (continued):
Sharing a sentence is not in itself a finding about the gene and the disease.
psoriasis (12 papers, 2009 to 2025). An autoimmune condition characterized by red, well-delineated plaques with silvery scales that are usually on the extensor surfaces and scalp. "IL-1β promotes the differentiation of Th17 cells to secrete IFN-γ, and IL-18 enhances IFN-γ-induced production of C-X-C motif chemokine 9 (CXCL9), CXCL10 and CXCL11, which migrate from dermis to epidermis causing chronic inflammatory activation of psoriasis." (PMID 39689159, 2024). "This study explores the regulatory roles and mechanisms of chemokines CXCL9, CXCL10, and CXCL11 in psoriasis." (PMID 40303401, 2025). "Our data suggest that STAT2 plays a role in the psoriasis pathogenesis by regulating the expression of CXCL11 and CCL5, and thereby attracting IFNγ-producing immune cells to the skin." (PMID 28472186, 2017). "In addition to those previously noted, cytokines like IFN-γ, TGF-β, CXCL9, CXCL10, IL-33 and CXCL11 play a significant role in psoriasis pathogenesis." (PMID 40303401, 2025). "The percentage of inflammatory cells expressing CXCL10 in AOSD patients was higher than that in normal control, eczema, and psoriasis groups, but the percentage of inflammatory cells expressing CXCL11 in AOSD patients was lower than that in eczema and psoriasis patients." (PMID 28436448, 2017). "It is therefore tempting to speculate that STAT2 plays a role in the pathogenesis of psoriasis by specifically recruiting Th1 cells to the inflammatory site through its regulation of CXCL11 and CCL5." (PMID 28472186, 2017). "Multiple chemokines have higher expression levels within the lesion-prone skin of psoriasis sufferers, including the CXC chemokine family members CXCL9, CXCL10, and CXCL11, with increased expression of CXCL9/10 being characteristic of psoriasis." (PMID 40303401, 2025). "Proteins related to the central disease‐driving pathways of psoriasis, namely the TH1 (CCL3, CCL4, CXCL9, CXCL10, CXCL11, TNFα) and TH17 pathway (CXCL1, CCL20, IL‐17A, IL‐12B) were found elevated in lesional skin across both studies." (PMID 40970551, 2025). "The mean percentages of inflammatory cells from psoriasis skin lesions expressing CXCL9, CXCL10, CXCL11 and CXCR3 were 3.0% ± 3.4%, 3.0% ± 2%, 46.8% ± 17.7% and 21.2% ± 19.5%, respectively." (PMID 28436448, 2017). "By contrast, the percentage of inflammatory cells expressing CXCL11 in AOSD skin lesions was lower than that in eczema (p = 0.006) and psoriasis (p = 0.035) patients." (PMID 28436448, 2017). "However, the frequency of CXCL11-stained cells was significantly lower in AOSD than eczema and psoriasis." (PMID 28436448, 2017).
asthma (11 papers, 2015 to 2024). "A previous study of cord blood found associations between higher CXCL10 levels in infancy and asthma later in life, contradictory to our findings, but decreased levels of CXCL11 that were associated with allergic sensitization later in life, in line with our study." (PMID 38270326, 2024). "Intriguingly, the relative abundance of nasal Moraxella was positively associated with systemic and airway eosinophil counts, suggesting associations with allergic inflammation, as well as with asthma-associated pro-inflammatory chemokine CXCL11 and TNF levels in bronchial lavage fluid." (PMID 29885665, 2018). "In biopsies, there was also downregulation of the important mast cell chemoattractants CXCL10 and CXCL11 which promote mast cell migration to the ASM in mild steroid-naive asthma through the airway mast cell chemokine receptor CXCR323." (PMID 38686450, 2024). "In both non-asthma and asthma groups, simultaneous SP-A treatment significantly reduced antiviral genes and CXCL11 mRNA expressions in a dose dependent manner." (PMID 39599822, 2024). "Southworth found that higher expression of CXCL11 appeared in moderate asthma after rhinovirus infection." (PMID 35187081, 2022). "Ghebre reported that sputum CXCL9 level and serum CXCL11 level increased during asthma exacerbation." (PMID 35187081, 2022). "Sputum CCL5 and CXCL11 levels were substantially higher in subjects with asthma than in subjects with COPD, with area under the ROC curves (ROC AUCs) of 0.74 (95% CI, 0.67-0.82; P < .0001) and 0.72 (95% CI, 0.64-0.80; P < .0001), respectively." (PMID 25129678, 2015). "Serum CXCL9 levels in asthma patients are positively correlated with CXCL10 and CXCL11 levels, which are also CXCR3 ligands." (PMID 37005469, 2023). "The researchers found that the expression of mRNA-encoding TSLP, TARC/CCL17, MDC/CCL22 and IP-10/CXCL10, other than I-TAC/CXCL11 and I-309/CCL1, were significantly increased in severe asthma and COPD patients compared to the non-smoking control group." (PMID 34301307, 2021).
colon adenocarcinoma (11 papers, 2021 to 2025). "Upregulation of CXCL11 was associated with better prognosis in colon adenocarcinoma, which promoted antitumor immunity to benefit survival, identified as an independent prognostic biomarker in colon adenocarcinoma patients." (PMID 35812403, 2022). "Consistent with our research, previous study have revealed that CXCL11 expression is significantly upregulated in colon adenocarcinoma, and upregulation of CXCL11 expression is associated with a better prognosis." (PMID 34819038, 2021). "CXCL11 was found to be an independent biomarker for prognosis in patients with colon adenocarcinoma." (PMID 40822974, 2025). "CXCL11 expression was significantly elevated in both colon adenocarcinoma and rectal adenocarcinoma; thus, CXCL11 could be used as a marker of colon adenocarcinoma." (PMID 37889013, 2023). "Notably, CXCL11 can promote antitumor immunity to benefit survival, as in patients with colon adenocarcinoma." (PMID 35087741, 2021). "In the present study, we first discovered that CXCL11 mRNA expression was upregulated in both colon adenocarcinoma (COAD) and rectal adenocarcinoma (READ) samples in the TCGA database, but only the upregulation in COAD had prognostic value." (PMID 33777950, 2021).
glioma (10 papers, 2011 to 2025). A benign or malignant brain and spinal cord tumor that arises from glial cells (astrocytes, oligodendrocytes, ependymal cells). "In the training cohort, CXCL14 (P value < 0.001), CXCL9 (P value < 0.05), CXCL10 (P value < 0.001), CXCL11 (P value < 0.001), CXCL6 (P value < 0.001), and CXCL1 (P value < 0.001) were enriched in the IDH wide-type gliomas." (PMID 34603309, 2021). "In gliomas, abnormal expression profiles of CXCL9, CXCL10, CXCL11, and CXCL12 were noticed among different pathological grade gliomas, implying their potential relationship with glioma progression." (PMID 34603309, 2021). "In the combination study of oncolytic adenovirus armed with murine chemokine CXCL11 and B7H3 CAR T-cells, it was shown that CXCL11-oAd improves the recruitment of CAR T-cells into the tumor sites and reprograms the immunosuppressive TME in immunocompetent mice C57Bl/6 with glioma GL261." (PMID 38396720, 2024). "CXCL9, CXCL10, CXCL11, CXCL12, and CXCL14 were filtered as main contributors of glioma progression." (PMID 34603309, 2021). "Glioma cell lines did not express CXCR3, CXCR4, CXCR6, CX3CR1, but high levels of CXCR7, which is a receptor for CXCL11 and CXCL12 and can mediate G-protein independent signals via arrestin." (PMID 26796342, 2016).
atherosclerosis (9 papers, 2015 to 2024). A disease characterized by the build-up of fatty material and calcium deposition in the arterial wall resulting in partial or complete occlusion of the arterial lumen. "CXCL11 can be detected in all stages of plaque development, and evidence suggests that together with chemokines, CXCL9/MIG and CXCL11/ITAC, it regulates T-cell trafficking in atherosclerosis." (PMID 36831031, 2023). "However, higher protein levels of CXCL10 as well as CXCL11 were detected in human and carotid atherosclerotic tissues whereas none of them were detected in normal vessel walls, highlighting that both proteins are playing an important role in the development of atherosclerosis." (PMID 26663990, 2015).
autoimmune thyroiditis (9 papers, 2021 to 2025). "Genes involved in antigen processing and presentation, autoimmune thyroid and cytokine receptor interaction signaling pathways were the most significantly enriched in the CXCL11‐positive group." (PMID 34047476, 2021). "These chemokines play an important role in the pathogenesis of thyroid autoimmune diseases, and studies have shown that IFN-γ induces the secretion and expression of CXCL10, CXCL9 and CXCL11 in a dose-dependent manner." (PMID 38567309, 2024).
Autoimmunity (9 papers, 2015 to 2025). The occurrence of an immune reaction against the organism's own cells or tissues. "Interestingly, expression of Cxcl10 and Cxcl11, both of which have macrophage chemoattractant roles and are linked to autoimmunity and neuroinflammation, was most markedly upregulated in Nlrp12−/− retinas." (PMID 35313917, 2022). "Previously, we developed a fusion protein that includes CXCL10 linked to the N-terminus of murine IgG1 Fc (CXCL10-Fc) for cancer therapy and CXCL11-Fc for therapy of autoimmunity." (PMID 39474427, 2024). "This motivated us to develop a fusion protein that includes murine IgG1 Fc linked to CXCL10 (CXCL10-Ig or CXCL10-Fc) for cancer therapy, and CXCL11 fused to the same construct for therapy of autoimmunity (CXCL11-Ig or CXCL11-Fc)." (PMID 34944943, 2021). "CXCL11 binds to the CXCR3 receptor, which is mostly expressed in Th1 cells, in the presence of foreign antigens, and has also been associated with higher risk of severe COVID, gastrointestinal inflammation and autoimmune disorders." (PMID 36609477, 2023). "We then assessed the associations of CXCL9, CXCL10, and CXCL11, that were different between groups, with clinical characteristics, diagnosis, and treatment responsiveness to identify biomarkers of inflammation in ILD with background autoimmunity." (PMID 33137121, 2020). "Our AUCs for serum CXCL9, CXCL10 and CXCL11 in the differential diagnosis of CVD–ILD from IPAF and IPF suggest that these serum chemokines may be diagnostic biomarkers of ILD with autoimmunity." (PMID 33137121, 2020). "The basic rational is that the stabilized form of chemokines that induce Tr1-like cells, among them CXCL12 and CXCL11, could be used for therapy of autoimmunity and GVHD, whereas stabilized CXCL10 would be used for cancer therapy." (PMID 26648938, 2015). "Serum CXCL9, CXCL10, and CXCL11 are potential biomarkers for autoimmune inflammation and predictors of the immunosuppressive therapy responses in ILD with background autoimmunity." (PMID 33137121, 2020). "This study demonstrated that in patients with CVD–ILD and IPAF with background autoimmunity, serum and BALF levels of CXCL9, CXCL10, and CXCL11 were significantly higher than those in patients with IPF." (PMID 33137121, 2020). "CXCL10 and CXCL11 have been suggested to have opposite activities with CXCL10 promoting and CXCL11 suppressing T-cell–mediated autoimmunity." (PMID 31167786, 2019). "Unlike the pro-inflammatory CXCL10, CXCL11 promotes the development of IL-10–producing regulatory T cells, which help control autoimmunity." (PMID 40969764, 2025). "Since CXCL11-mediated stimulation of CXCR3 has been consistently involved in the lymphocyte infiltration into the CNS in mice and humans upon CNS autoimmunity, we next addressed whether propionate-mediated GPR43 stimulation was able to affect the CXCL11-CXCR3 migration of IEL TCRαβ+ T-cells." (PMID 37264394, 2023). "Serum CXCL9, CXCL10, and CXCL11 may reflect autoimmune inflammation of ILD and work as biomarkers to predict the response to immunosuppressive therapy in the management of ILD with background autoimmunity." (PMID 33137121, 2020). "Our results suggest that high serum CXCL9, CXCL10, and CXCL11 levels may reflect reversible inflammation and that these chemokines are predictive biomarkers of the response to immunosuppressive therapy in ILD with background autoimmunity." (PMID 33137121, 2020).
Obesity (9 papers, 2021 to 2024). Accumulation of substantial excess body fat. "Interferon-γ–alpha T-cell chemoattractant (I-TAC/CXCL11) is a novel biomarker of inflammation in obesity, where an association between endothelial leukocyte stasis and increased risk of cardiovascular morbidity in obesity was suggested." (PMID 39273654, 2024). "Interferon-inducible T-cell alpha chemoattractant (I-TAC/CXCL11) is a novel biomarker of inflammation in obesity, belonging to the CXC chemokine family, which plays a role in the recruitment of T cells and other immune cells to sites of inflammation." (PMID 39408928, 2024). "Relevant studies showed that CXCL10 and CXCL11 are potential predictive molecules for obesity onset and CXCL1 expression level is related to adipocyte differentiation." (PMID 37889664, 2023). "A recent study reported CXCL10 and CXCL11 as potential biomarkers for the onset of adipose tissue inflammation during obesity with CXCL11 expression correlation with NF-κB expression." (PMID 36557031, 2022). "Research suggests that certain members of the CXCL family, particularly CXCL10 and CXCL11, could serve as potential indicators of adipose tissue inflammation in obesity." (PMID 39857642, 2024). "Data suggest that CXCL family members, specifically CXCL10 and CXCL11, may serve as potential biomarkers for the onset of adipose tissue inflammation during obesity." (PMID 39408928, 2024). "Additionally, a newer biomarker of inflammation in obesity is Interferon-inducible T-cell alpha chemoattractant (I-TAC/CXCL11), a member of the CXC chemokine family involved in recruiting T lymphocytes and other immune system cells to inflammation sites." (PMID 39857642, 2024). "In our study, we found a positive correlation between CAV1 expression and CXCLs (CXCL9, CXCL10, and CXCL11); this could be explained by the proinflammatory role and heightened presence of CXCLs in obesity." (PMID 37048092, 2023). "In obesity, the expression of CXCR7, CXCL11 and CXCL12 is increased, and CXCR7 neutralizing therapy with an anti-CXCR7 antibody can not only reduce macrophage infiltration and inflammation in obesity but also improve insulin resistance." (PMID 39582861, 2024). "Additionally, CXCR7 is expressed in adipose tissue, and its ligands CXCL11 and CXCL12 mediate macrophage chemotaxis and phagocytosis and contribute to inflammation during obesity." (PMID 39582861, 2024). "CNTNAP2, GLI2, DPT (dermatopontin), AEBP1, ITIH5, CXCL11, GDNF (glial cell derived neurotrophic factor), MCHR1, FLT3, ELANE (elastase, neutrophil expressed), OSMR (oncostatin M receptor) and IL15RA are involved in development of obesity, but these genes might be key for progression of HF." (PMID 34218797, 2021).
pulmonary fibrosis (9 papers, 2016 to 2025). Chronic progressive interstitial lung disorder characterized by the replacement of the lung tissue by connective tissue, leading to progressive dyspnea, respiratory failure, or right heart failure. "In SLE, Nielepkowicz-Goździńska A and others found that CXCL10 and CXCL11 are associated with the accumulation of neutrophils in the alveolar spaces of patients with SLE lung fibrosis, potentially contributing to interstitial fibrosis, providing some support for our hypothesis." (PMID 39185418, 2024). "Multiple studies have shown that chemokines such as CXCL9, CXCL10, and CXCL11 promote pulmonary fibrosis by recruiting fibrosis-related macrophages, but the role of CXCL14 in IPF has long been overlooked." (PMID 40842541, 2025). "CXCL11 prevented the development of BLM-induced lung fibrosis via the repression of aberrant vascular remodeling." (PMID 39548525, 2024). "At present, the association between some cytokines and pulmonary fibrosis in SLE have been demonstrated, such as CXCL10, CXCL11, IL-8 and so on." (PMID 36871016, 2023). "Studies have demonstrated an imbalance in the levels of angiogenic chemokines (ELR+ CXC chemokines [CXCL5 and CXCL8]) and angiostatic chemokines (interferon-inducible ELR- CXC chemokines [CXCL9, CXCL10, CXCL11]) in animal models of pulmonary fibrosis and lung tissue from patients with IPF." (PMID 39418259, 2024). "Interferon‐inducible T cell (I‐TAC, or CXCL11), a chemoattractant, has been found to attenuate bleomycin‐induced mouse model lung fibrosis with systemic treatment by inhibiting vascular remodeling." (PMID 34272836, 2021).
ZIKV infection (9 papers, 2017 to 2025). "Top selected ZIKV infection-associated genes from RPE cells are shown in a heatmap that includes multiple immune response genes, such as CCL5, CXCL11, CXCL1, IFNB1, IL6 and TNFSF10." (PMID 30046058, 2018). "Moreover, ZIKV infection induced an increase in the chemokines CCL3, CXCL9, and CXCL8, while CCL4 and CXCL11 were significantly decreased." (PMID 33430059, 2021).
lymphoma (8 papers, 2010 to 2022). A malignant (clonal) proliferation of B- lymphocytes or T- lymphocytes which involves the lymph nodes, bone marrow and/or extranodal sites. "Epstein-Barr viruses infected B cells shuttles functional mature EBV-encoded miRNAs in EVs to immature monocyte-derived dendritic cells to downregulate the expression of CXCL11/ITAC in primary EBV-associated lymphomas." (PMID 32082312, 2020). "CXCL11 is a chemokine known to mediate the migration of activated T-cells, and has been described as an immunomodulatory target of miRNA in primary lymphoma and has also demonstrated potent antitumor activity in an animal model." (PMID 24922518, 2014). "EBV-Infected B cells secrete EBV-encoded miRNAs, the EBV-miRNAs function due to internalization of exosomes by MoDC, resulting from dose-dependent miRNA mediated repression of confirmed EBV target genes including CXCL11/ITAC, immunoregulatory gene down-regulated in primary EBV-associated lymphomas”." (PMID 33381452, 2020). "Take, for example, exosomes from Epstein Barr Virus (EBV) transformed lymphoblastoid B cells, containing miRNA: when exposed to dendritic cells (DCs), they lead to dose-dependent suppression of the immunoregulatory gene CXCL11/ITAC - known to be a target of EBV in promoting lymphomas." (PMID 28936255, 2016). "In addition, virus-encoded miRNAs can dysregulate host cell function, such as Epstein Barr virus (EBV) miRNA repression of host cell CXCL11/ITAC, inducing EBV-associated lymphomas." (PMID 25191859, 2014). "Indeed miR155 has been shown to lead to lymphoma in transgenic mice and the EBV encoded miRNA BHRF1-3 appears to suppress an anti-tumour, T-cell-attracting chemokine, CXCL-11." (PMID 20161707, 2010). "There are few studies on the expression of CXCLs in lymphoma except CXCL8 and CXCL11 in DLBCL10,11." (PMID 35181719, 2022). "In contrast, a rise in CXCL11 had no impact on the angiogenesis of mouse EL4 lymphoma cells nor human CRC." (PMID 31216755, 2019).